RAF1 (Raf-1 proto-oncogene, serine/threonine kinase)
Diseases named in the same sentence as RAF1 in open-access papers (continued):
Sharing a sentence is not in itself a finding about the gene and the disease.
glioma (37 papers, 2012 to 2026). A benign or malignant brain and spinal cord tumor that arises from glial cells (astrocytes, oligodendrocytes, ependymal cells). "Besides, mutations in ERC2-RAF1 fusion have been detected in ganglio-gliomas, being RAF1 involved in MAP kinase pathway activation." (PMID 35877760, 2022). "Indeed, several of the R-loop-forming genes we identified in NSPCs show rearrangements and mutations in human low-grade and high-grade gliomas, including Raf1, Daxx, Fgfr1, Lztr1, and H3F3A 46–48, which warrants further studies of the role of R-loops in brain cancer development." (PMID 35927309, 2022). "MiR-320e has been identified as a potential therapeutic target up-regulating the PBX2/Raf-1/MAPK axis in glioma." (PMID 38455766, 2024). "Three candidate genes (RAF1, RB1, and SP1) were selected through KEGG pathway analysis, as all three genes were previously found to be associated with glioma pathogenesis." (PMID 36980172, 2023). "Treatment with eckol was also noted to induce a marked suppression of the PI3K and Akt activities, and completely inhibit Ras-Raf-1 interaction and Raf-1 and Erk activations in the sphere-forming glioma stem-like cells." (PMID 34440090, 2021). "Treatment with eckol caused a marked suppression of PI3K-Akt activities, and completely inhibited Ras-Raf-1 interaction and Raf-1 and Erk activations in sphere-forming glioma stem-like cells." (PMID 34063013, 2021). "Several studies showed that miR-7-5p is downregulated in the peripheral blood of glioblastoma patients, glioma cell lines and human glioma tissue, or in the microvasculature of these tumors themselves and targeting the RAF1 oncogene." (PMID 34199498, 2021). "EGFR and RAF1 fusions additionally displayed substantial cancer type-specificity, with 65% of 5′ EGFR fusions occurring in gliomas and 69% of 5′ RAF1 fusions occurring in thyroid carcinomas (THCAs)." (PMID 34795215, 2021). "Results revealed that cannabinoids induce apoptosis signal via cannabinoid receptors, ceramide accumulation, and Raf1/extracellular-signal-regulated kinase activation in two subclones of C6 glioma cells." (PMID 34502095, 2021). "This was attributed to the combined effects of the CPT and the Raf-1 gene silencing of siRaf-1 in glioma tissues." (PMID 31779126, 2019). "Pleomorphic xanthoastrocytoma is a circumscribed glial neoplasm that is genetically characterized by concurrent CDKN2A homozygous deletion and BRAF p.V600E mutation (or less commonly BRAF or RAF1 fusion)." (PMID 29880043, 2018). "Recent results have further demonstrated that SHP-2 binds and dephosphorylates both wild-type and oncogenic HRAS on Tyr32 in astrocytes and glioma cells, an event that increases RAS association with RAF-1 and downstream MEK/ERK activation." (PMID 27582544, 2016). "Increased miR-320 level in U87 and U251 cells was achieved through miR-320 mimic transfection and the effect of which on glioma cells growth, proliferation, cell cycle, apoptosis and activation of Raf-1/MAPK pathway was determined using MTT, colony formation, flow cytometry and western blot assays." (PMID 28934982, 2017). "PBX3 knockdown significantly suppressed Raf-1 phosphorylation, suggesting PBX3 might aggravate glioma through promoting the activation of Raf-1, and subsequent Raf-1 mediated MAPK cascade and apoptosis inhibition." (PMID 28934982, 2017). "On the other hand, Rictor silencing was shown to activate Raf-1-MEK-ERK pathway in glioma cells." (PMID 23555046, 2013). "Additional RAF1 fusions, contributing to constitutive MAPK activity, have been documented across gliomas and other tumor types." (PMID 41514664, 2026).
glioma (continued). "Specifically, PBX3 knockdown significantly reduced the increased phosphorylation level of Raf-1, p38, and ERK1/2 in glioma cells." (PMID 34006845, 2021). "MPEG-PCL-TAT micelles were loaded with anti-rat Raf-1 siRNA (siRaf-1) and CPT and then evaluated for their brain uptake efficiency on a C6 glioma model." (PMID 31779126, 2019). "Differential expression was found, however, with increased mean RAF1 transcripts and MAPK1 abundance and decreased mean ARAF transcripts in IDH-mutant gliomas; yet only low ARAF expression correlated with improved patient survival." (PMID 27852048, 2017). "However, Rictor, a component of the mTOR complex, induces glioma cell migration, increasing MMP-9 expression through the Raf-1-MEK-ERK signaling pathway." (PMID 36980765, 2023). "On the base of presented results, authors made a conclusion that eckol may enhance the sensitivity of glioma stem-like cells to anticancer therapies such as ionizing radiation or chemical drugs via inhibition of PI3K-Akt and Ras-Raf-1-Erk pathways." (PMID 34440090, 2021). "The results showed that CCND1, CDC42, RAF1, and CHEK1 were highly expressed in gliomas." (PMID 33676540, 2021). "The results suggested miR-320 might functions through the PBX3/Raf-1/MAPK axis, and miR-320 oligonucleotides might be a potential cancer therapeutic for glioma." (PMID 28934982, 2017). "MiR-320 may suppress glioma cells growth and induced apoptosis through the PBX3/Raf-1/MAPK axis, and miR-320 oligonucleotides may be a potential cancer therapeutic for glioma." (PMID 28934982, 2017). "Sphere-forming glioma cells treated with eckol extracted from Ecklonia cava showed a reduction in self-renewal, sphere formation and anchorage-independent growth ability of glioma CSCs, acting on PI3K/AKT and RAF-1/ERK signaling pathways, which regulate the maintenance of CSCs." (PMID 35736190, 2022). "To determine whether this was true in our glioma models, we quantified RAS-GTP levels in response to short-term MEKi versus control using a RAF1-RAS binding domain (RAF1-RBD) based immunoprecipitation to extract the fraction of RAS that is GTP-bound and able to bind RAF1." (PMID 40900823, 2025). "Also implicated in LGG pathogenesis is the BRAF-MAP kinase pathway, but no significant changes in RAF1, BRAF, and MAPK1 methylation were observed in IDH-mutant glioma in comparison with IDH-wildtype." (PMID 27852048, 2017).
prostate carcinoma (30 papers, 2004 to 2024). A carcinoma that arises from epithelial cells of the prostate gland. "The other is that we have revealed a novel molecular mechanism underlying the hyperactivation of the Raf1/MEK/ERK1/2 pathway in prostate cancer." (PMID 27213581, 2016). "Amplification of members of the MAPK pathway was associated with androgen independent prostate cancer, and co-expression of RAF1, ERBB2/HER2 and c-FOS would lead to this phenotype." (PMID 20805891, 2010). "Initially, the phosphorylated form of RKIP (pS153) indicative of Raf-1 activation was detected in association with centrosomes and prophase/prometaphase kinetochores in a number of cells and tissues including prostate cancer cells, brain hippocampus, and head and neck tumor tissues." (PMID 17214889, 2007). "Moreover, ERα and ERβ interact directly with the membrane associated Src complex to trigger prostate cancer cell proliferation through the RAF-1/Erk-2 signal transduction pathway." (PMID 15318942, 2004). "As one of the best characterized signaling pathways involved in the progression of prostate cancer, the Raf1/MEK/ERK1/2 pathway is under control by the small GTPase ARF1 which is also upregulated." (PMID 27213581, 2016). "The function of ARF1 in regulating prostate cancer cell growth is likely mediated through activating the Raf1/MEK/ERK1/2 pathway." (PMID 27213581, 2016). "In prostate cancer, presence of Raf-1 and MEK1 in conjunction with elevated ERK1 and ERK2, and their phosphorylated forms, suggests that stimulation of cell proliferation could be triggered by IL-6 via the ERK pathway." (PMID 22046506, 2012). "Based on these findings, we postulate that, in prostate cancer, elevated expression/activation of ARF1 promotes the activation of the Raf1/MEK/ERK1/2 pathway." (PMID 27213581, 2016). "This study was performed in prostate cancer tissues which were evaluated for PSA, PSMA, RKIP, Raf-1, MEK-1, ERK1/2, p-Akt (T308/S473), and NF-κB (p50/p65) expression by immunohistochemistry analysis using isoform-specific antibodies." (PMID 23991415, 2013). "Raf-1, MEK-1, ERK-1, and ERK-2 were, respectively, expressed by 9 (47.3%), 10 (52.6%), 12 (63.1%), and 7 (36.8%) of all prostate carcinomas." (PMID 23991415, 2013). "In a xenograft mouse model for prostate cancer, exogenous RKIP expression suppresses invasion and metastasis, and this reduction correlates with Raf-1 inhibition." (PMID 17214889, 2007). "As an example, in prostate cancer rearrangements occurred between untranslated exon 1 of SLC45A3 (a prostate-specific androgen responsive gene) and exon 8 of BRAF (GenBank GU149303) or between exon 13 of ESRP1 (an epithelial splicing regulatory protein) and exon 6 of RAF1 (GenBank GU149302)." (PMID 25473895, 2015). "For ETS fusion-negative prostate cancers subtypes, novel gene fusions have also been identified, including SLC45A3:BRAF, ESRP1:RAF1, SLC45A3:BRAF, ESRP1:RAF1, C15orf21:Myc, EPB41:BRAF, and TMEM79:SMG5." (PMID 23957008, 2013).
glioblastoma (27 papers, 2012 to 2025). The most malignant astrocytic tumor (WHO grade IV). "It has also been shown that increased RAF1 levels are present in human glioblastoma samples and that they may be associated with microvascular proliferation." (PMID 32349263, 2020). "The integrated genomic and transcriptomic analysis of the tumors showed EGFR, PDGFRA, FGFR3, NF1, and BRAF/RAF1 mutually exclusive alterations within the glioblastoma IDH-wild-type category." (PMID 34572759, 2021). "Moreover, curcumin inhibits human cytomegalovirus by downregulating heat shock protein 90 (Hsp90), whereas beta-elemene inhibits formation of the Hsp90/Raf-1 complex, thereby inducing apoptosis in glioblastoma cells." (PMID 29636777, 2018). "Since RKIP is considered to be an endogenous inhibitor of the Raf-1/MEK/ERK pathway we evaluated whether RKIP inhibition on glioblastoma cells modulates this pathway." (PMID 22292035, 2012). "Previous studies have suggested that USP10 can promote Raf-1 protein expression and activate the Raf-1/MEK/ERK pathway in endometriosis and glioblastoma." (PMID 39430239, 2024). "This situation applies to RAF1, BDNF, SATB1, CDK6, and GABRA1, which have an important function in the pathogenesis of glioblastoma." (PMID 32349263, 2020). "Further study showed that bELE disrupts the formation of the Hsp90/Raf‐1 complex and subsequently leads to the deactivation of Raf‐1, inhibition of the ERK signaling pathway, and promotion of the apoptosis of glioblastoma cells." (PMID 28297578, 2017). "For EGFR pathway activation, the activity scores for the EGFR, MAPK, RAF1, and MEK signatures were higher in the G-CIMP- glioblastomas in the CGGA." (PMID 25277177, 2014). "This analysis enrichment of the Ras/RTK (EGFR, MAPK, RAF1, and MEK) in G-CIMP- glioblastomas is relative to the G-CIMP+ glioblastomas in both the CGGA and the REMBRANDT dataset." (PMID 25277177, 2014). "On the other hand, a recent study showed that overexpression of miR-424 strongly suppressed cell proliferation and migration rate in glioblastoma cells, by targeting genes such as KRAS, RAF1, and MAP2K1, from the epidermal growth factor receptor (ERBB) signaling pathway." (PMID 37047673, 2023). "In addition, treatment with β-elemene induced human glioblastoma multiform cell line U87MG by disrupting the formation of the Hsp90/Raf-1 complex, leading to Raf-1 deactivation and ERK pathway inhibition." (PMID 33801899, 2021). "In addition, miR-7 also can inhibit glioblastoma cell invasion by downregulating the expression levels of p-ERK1/2, p-AKT, Raf-1, and cyclin D1." (PMID 26516313, 2015).
gastric cancer (22 papers, 2011 to 2025). A primary or metastatic malignant neoplasm involving the stomach. "We found a significant association between RAF-1 rs1051208 G/C and risk of gastric cancer (P< 0.05)." (PMID 29118938, 2017). "We investigated two single nucleotide polymorphisms (SNPs) of TNF-α -1031 and RAF-1 rs1051208- in a gastric cancer in an Iranian population." (PMID 29118938, 2017). "Furthermore, Raf1 has been linked to tumors of the parotid gland, stomach cancer, and renal cell carcinoma." (PMID 37505851, 2023). "The results indicated that C allele in RAF1 gene plays a role in susceptibility to gastric cancer." (PMID 29118938, 2017). "Together with TRPC1 and TRPC3, a role for TRPC6 in TGFβ-induced EMT was described in gastric cancer cells, mediated via the Ras/Raf1/ERK1/2 signaling cascade." (PMID 34360952, 2021). "The results of a case control study in Chilean population showed that the polymorphisms in the proteins of the RAS/RAF/MEK/ERK pathways, such as rs3729931 (RAF1), rs45604736 (HRAS), rs2283792, and rs9610417 (MAPK1), are associated with gastric cancer." (PMID 34484153, 2021). "TRPC3— a role for TRPC3 in TGFβ-induced EMT was described in gastric cancer cells, one mediated via the Ras/Raf1/ERK1/2 signaling cascade." (PMID 34360952, 2021). "In conclusion, using a case-control approach we found that rs3729931 (RAF1), rs45604736 (HRAS), rs2283792, and rs9610417 (MAPK1) are associated with gastric cancer." (PMID 30597917, 2018). "We found significant association of the SNPs RAF1 rs3729931, HRAS rs45604736, and MAPK1 rs2283792 and rs9610417 with gastric cancer." (PMID 30597917, 2018). "In conclusion, this study suggests that RAF1 rs3729931, HRAS rs45604736, MAPK1 rs2283792, and MAPK1 rs9610417 are associated with gastric cancer." (PMID 30597917, 2018). "In gastric cancer (GC), by targeting SLC34A2, the overexpression of miR-939 in GC cells significantly decreased Raf-1, p-MEK1/2 and p-ERK expression levels for suppressing the chemoresistance and metastasis of GC34." (PMID 29403024, 2018). "To date, SNPs of the gene RAF-1 (rs1051208) have not been evaluated in gastric cancer." (PMID 29118938, 2017).
osteosarcoma (19 papers, 2013 to 2025). A usually aggressive malignant bone-forming mesenchymal neoplasm, predominantly affecting adolescents and young adults. "For example, adding recombinant TIMP-1 to osteosarcoma cells activated RAS via phosphorylation of RAF1." (PMID 41002380, 2025). "In osteosarcoma, Cyr61 was found to promote the migration and invasion of osteosarcoma by regulating the Raf-1/MEK/ERK signaling pathway." (PMID 37626810, 2023). "Evidence also suggests that miR-16 interacts with the 3′-UTR of IGF1R, KRAS, and RAF1, thereby reducing osteosarcoma cell proliferation through the CRAF–MAPK pathway." (PMID 38111008, 2023). "Integrin αVβ5 was reported in osteosarcoma cells which was involved in promotion of the EMT with signal transduction pathway included Raf-1, MEK, ERK, and Elk-135." (PMID 28084395, 2017). "In this study, we determined that Cyr61 promoted mesenchymal transformation in osteosarcoma through the Raf-1/MEK/ERK signaling cascade." (PMID 25326651, 2014). "COPS3 interacts with Raf-1 and activates MEK/ERK signaling to regulate osteosarcoma metastasis via autophagy." (PMID 37626810, 2023). "A previous study also revealed that COPS3 played a vital role in linking Raf-1/MEK/ERK pathway and autophagic regulation in osteosarcoma." (PMID 35903293, 2022). "In osteosarcoma, Cyr61 promotes EMT and the metastasis of tumor cells through the Raf-1/MEK/ERK/Elk-1/TWIST-1 signaling pathway." (PMID 34970415, 2021). "While Raf-1 appeared in COPS3 immunoprecipitates, the antibody against Raf-1 was also able to pull down COPS3 in both 143B and HOS osteosarcoma cell lines, confirming direct binding between COPS3 and Raf-1." (PMID 29970115, 2018). "Our results indicate that Cyr61 promotes the EMT of osteosarcoma cells by regulating EMT markers via a signal transduction pathway that involves αvβ5 integrin, Raf-1, MEK, ERK, and Elk-1." (PMID 25326651, 2014). "Moreover, the expression of RAF1, a part of the MAPK/ERK pathway, is related to cell proliferation in osteosarcoma." (PMID 32873319, 2020). "Several candidate osteosarcoma oncogenes found in a transposon-based forward genetic screen in mice are also hypomethylated and overexpressed in human osteosarcoma compared to normal osteoblasts, including SEMA4D, RAF1 and PAK1." (PMID 29056713, 2016). "In addition, Cyr61-promoted EMT is mediated by αvβ5 integrin, Raf-1, mitogen-activated protein kinase kinase (MEK), extracellular signal-regulated kinase (ERK), and Elk-1 signaling pathways, and may be involved in the regulation of EMT in osteosarcoma." (PMID 25326651, 2014).
colon carcinoma (18 papers, 2013 to 2025). "In the light of these considerations, we assayed the ability of TM treatment to influence signal transduction through the Raf1/MEK/ERK pathway in colon cancer cells bearing different status of BRAF." (PMID 31083627, 2019). "Clove oil was also tested in Caco-2 colon cancer cells, where it increased programmed cell death and inhibited proliferation signaling by modulating Raf-1 activity; in HT-29 cells, a nanoparticulate system containing clove oil inhibited cell proliferation in a selective manner." (PMID 39683236, 2024). "In colon cancer cells, Raf-1/ERK signaling could activate autophagy through stimulating the phosphorylation of G-alpha-interacting protein." (PMID 29970115, 2018). "Amino acids were found to inhibit Raf-1 activation, which interfered with ERK1/2-dependent autophagy control in colon cancer HT-29 cells." (PMID 32964050, 2020). "In addition to the increased expression of DEPP, the phosphorylation and the activation of Raf1 and ERK were dramatically induced in the colon cancer cells in response to the hypoxic condition." (PMID 29440765, 2018). "Moreover, it has been shown that PHLPP dephosphorylates Ser338, a key activation site on RAF1, and inhibits the downstream signaling through RAF/MEK/ERK in colon cancer cells." (PMID 26760962, 2016).